IGHV3-38 (immunoglobulin heavy variable 3-38 (non-functional))
Description:
Probable non-functional open reading frame (ORF) of V region of the variable domain of immunoglobulin heavy chains. Non-functional ORF generally cannot participate in the synthesis of a productive immunoglobulin chain due to altered V- (D)-J or switch recombination and/or splicing site (at mRNA level) and/or conserved amino acid change (protein level). Immunoglobulins, also known as antibodies, are membrane-bound or secreted glycoproteins produced by B lymphocytes. In the recognition phase of humoral immunity, the membrane-bound immunoglobulins serve as receptors which, upon binding of a specific antigen, trigger the clonal expansion and differentiation of B lymphocytes into immunoglobulins-secreting plasma cells. Secreted immunoglobulins mediate the effector phase of humoral immunity, which results in the elimination of bound antigens. The antigen binding site is formed by the variable domain of one heavy chain, together with that of its associated light chain. Thus, each immunoglobulin has two antigen binding sites with remarkable affinity for a particular antigen. The variable domains are assembled by a process called V-(D)-J rearrangement and can then be subjected to somatic hypermutations which, after exposure to antigen and selection, allow affinity maturation for a particular antigen.
Synonyms: IGHV338; VH
Gene: Immunoglobulin variable (V) gene on chromosome 14 (106,410,493 to 106,411,021, reverse strand). Ensembl gene ENSG00000211958.
Subcellular location: Secreted; Cell membrane
Gene Ontology:
Molecular function: antigen binding
Biological process: immunoglobulin mediated immune response
Cellular component: extracellular region; plasma membrane
Homologues: Paralogues in human: IGHV3-66 (86% identical), IGHV3-23 (85% identical), IGHV3-53 (85% identical), IGHV3-74 (84% identical), IGHV3-48 (83% identical), IGHV3-11 (82% identical), IGHV3-64 (82% identical), IGHV3-21 (81% identical), IGHV3-7 (81% identical), IGHV3OR16-13 (81% identical), IGHV3-30 (80% identical), IGHV3-33 (80% identical), and 65 more.